BRCA1 (BRCA1 DNA repair associated)
Diseases named in the same sentence as BRCA1 in open-access papers (continued):
Sharing a sentence is not in itself a finding about the gene and the disease.
tumor (continued). "Since blocked replication forks cannot be restarted without the help of PARP1/2, SSB inevitably lead to more severe DSB; hence, tumor cells lacking active BRCA1 or BRCA2 are sensitive to a PARP inhibitor molecule." (PMID 37569269, 2023). "Hence, both treatment groups exhibited reduced tumor volumes, which implied importance of BRCA1 and BRCA2 proteins as tumor suppressors p play role on tumor volume reduction." (PMID 36631481, 2023). "It was therefore of relevance to determine if and how differences in quantity of pre-existing TILs might affect the anti-tumour efficacy and immune response of combined PARP and WEE1 inhibition in the BRCA1/2 wild-type TNBC models." (PMID 37582853, 2023). "This is consistent with the OC-predisposing genes BRCA1 and BRCA2, where loss of the wild-type allele is not always observed in tumour cells from carriers of pathogenic variants in these CPGs." (PMID 36833203, 2023). "Yet, while the possibility of tumor contamination cannot be excluded for each case, it is unlikely to be the cause of the WBC BRCA1 methylation observed for several reasons." (PMID 38053165, 2023). "Earlier work also suggests that germline BRCA1 and BRCA2 pathogenic variants are unlikely to be found in patients with tumours of mucinous histology (0 to 4%)." (PMID 37076566, 2023). "Altogether, these results reveal that high peripheral WBC miR-155-5p acts as a tumor suppressor in BC and as an oncogene in OC, regardless of the methylation status of BRCA1." (PMID 37240365, 2023). "In addition, we have identified baseline tumour-infiltrating lymphocyte (TIL) levels as a potential predictive biomarker of response to PARPi, WEE1i and immunotherapies in BRCA1/2 wild-type TNBC." (PMID 37582853, 2023). "BRCA1 and BRCA2 are tumour suppressor genes that produce proteins with vital roles in DNA repair." (PMID 37108451, 2023). "Tumor DNA sequencing in MBC is currently not yet common in clinical practice and is mostly reserved for the determination of the mutational status of the BRCA1/BRCA2, PIK3CA, and, more rarely, the ESR1 and ERBB2 genes." (PMID 36980613, 2023). "The high-frequency keywords of PROC research included chemotherapy, expression, apoptosis, activation, tumor microenvironment, PARP inhibitors (Olaparib, niraparib, rucaparib), pazopanib, maintenance therapy, BRCA1/2, PD-L1 expression, etc., which were regarded as the hotspots in PROC research." (PMID 37342181, 2023). "Another tumor suppressor gene, BRCA1, regulated lipogenesis by interacting with the phosphorylated form of acetyl coenzyme A carboxylase alpha (P-ACCA) through its tandem of BRCA1 C terminus (BRCT) domains." (PMID 37110218, 2023). "Analysis of the 48 PARPi-resistant BRCA1-deficient (32 KB1P and 16 KB1PM tumors) tumors revealed that 60% (29/48) of the tumors had restored the capacity to form RAD51 foci, including one tumor with a mixed pattern (RAD51-IRIF-positive and -negative areas)." (PMID 37209095, 2023). "Here, one out of 116 tumors revealed BRCA1 methylation in the tumor tissue, and this patient was negative for WBC BRCA1 methylation." (PMID 38053165, 2023). "These mutants have yielded surprising results, revealing that the E3 ligase activity within the RING finger region is not crucial for BRCA1’s role as a tumor suppressor." (PMID 37762577, 2023). "BRCA1, BRCA2, ATM, PALB2, and BAP1 were the DNA damage response GA found in our tumor samples." (PMID 36831055, 2023). "In 2005, two studies showed that the inhibition of PARP1 activity is specifically cytotoxic in cells lacking functional forms of the tumor suppressors BRCA1 or BRCA2." (PMID 37509303, 2023). "Since BRCA1 also harbors a Zn(II)-complexing RING finger structure, this tumor suppressor may also represent a potential target." (PMID 37762697, 2023). "Interestingly, among the three ER ≥ 10% tumors revealing concordant tumor and WBC BRCA1 methylation, two revealed a basal-like profile, while the remaining one was classified as luminal A." (PMID 38053165, 2023).
tumor (continued). "Therefore, we would expect that the direct role played by BRCA1 in the control of ERα-mediated transcription reduces oestrogen’s effects on proliferation, angiogenesis, and TME-mediated tumour growth." (PMID 36230510, 2022). "We show that xenograft tumours lacking BRCA1 or BRCA2 are hypersensitive to pyridostatin and that the in vivo activity of this compound is similar to that of the PARPi talazoparib." (PMID 35107878, 2022). "One tumor, with BRCA1 promoter methylation, was HRD according to CHORD but not to the BRCA1/2-like classifier." (PMID 35662281, 2022). "Immunohistochemistry analysis of tumor xenograft samples suggested that in the radiation-treated group, circNEIL3 knockdown elevated the expression of γH2AX, AIM2, cleaved caspase-1, and GSDMD, but reduced the levels of PIF1 and BRCA1." (PMID 35190532, 2022). "In 2005, two studies revealed that tumor cells lacking BRCA1 or BRCA2 proteins are selectively vulnerable to PARPi." (PMID 35203410, 2022). "Unfortunately, the status of BRCA1/does not always correlate with tumor sensitivity to PARPi therapy." (PMID 36533080, 2022). "In preclinical models, PARPi has demonstrated synergy with ICIs in a variety of tumor models regardless of BRCA1/2-defect." (PMID 35572596, 2022). "This is due to the fact that many other types of tumor cells do not have BRCA1/2 germline mutations, but instead have other intracellular causes mediating HRR defects, resulting in the sensitivity of these tumor cells to PARP inhibitors." (PMID 36012144, 2022). "Western blot analysis showed that only the PTDSS2 protein level was stably elevated from both Brca1-MT mammary glands and tumor tissues of Brca1-MSK mice, but not PTDSS1." (PMID 35025764, 2022). "Apart from RAD51C, none of the high HRD tumours harboured biallelic loss of other known HRD drivers, such as BRCA1 or BRCA2." (PMID 35039523, 2022). "Furthermore, patients with BRCA1 methylated and HRD HGSOC have better prognosis than unmethylated HR proficient tumours." (PMID 35326684, 2022). "BRCA1 and BRCA2 tumour suppressors have key roles in maintaining genome integrity." (PMID 35107878, 2022). "Tumour testing, at least for BRCA1/2 genes, is recommended for all women testing negative for germline PVs." (PMID 36010882, 2022). "Inhibition of PARP1 alone is not lethal for normal cells, but in the absence of BRCA1/2, it becomes cytotoxic for tumor cells." (PMID 35203410, 2022). "Knowledge scores and poor recall of tumour genetic testing results suggest that HGSOC patients may benefit from educational resources and/or post-test genetic counselling following receipt of BRCA1/2 tumour genetic test results." (PMID 35418215, 2022).
tumor (continued). "At the 70% ERα+/ERα−ratio, MDA-MB-231Trans−ER and MDA-MB-231WT cell models showed the strongest cell invasion and migration in vitro as well as the highest M2 macrophage polarization and VEGR, TNF-α, BRCA1, and HER2 expression levels in the tumor microenvironment." (PMID 36118080, 2022). "Our results show that MED1 regulates the expression of the BRCA1-dependent transcripts p21 and GADD45α, suggesting that MED1 may contribute to the anti-tumor cell cycle regulatory function of BRCA1." (PMID 36229463, 2022). "Additionally, not all gBRCAm tumours have dysfunctional homologous recombination (HR), for instance due to the type of BRCA1 mutation or restored HR by genetic reversion of the underlying BRCA mutation, and could biologically be considered as homologous recombination proficient." (PMID 35124703, 2022). "BRCA1/2 positive patients contributed towards only 6.41% of other non-TNBC tumor IHC subtypes (n = 10/156) using Fisher’s Exact test (p value = 0.004)." (PMID 35710434, 2022). "Combined, these findings confirmed our previous results, where we saw that MYC expression directly hinders immune infiltration in BRCA1-mutant tumors and underscore that the decreased immunogenicity does not result from different tumor latencies or sizes." (PMID 36323660, 2022). "The staining of BRCA1, ABI1, and EIF3D was medium in tumor tissue but low in normal tissue." (PMID 36233273, 2022). "Looking at the average number of BRCA1 and BRCA2 variants detected in the tumor and non-tumor samples, the GeneReader and the Ion S5TM each found on average 11.5 mutations per sample." (PMID 35251494, 2022). "Ligands that bind and stabilise G‐quadruplexes (G4s) have recently emerged as a class of compounds that selectively eliminate the cells and tumours lacking BRCA1 or BRCA2." (PMID 35107878, 2022). "BRCA1 and BRCA2 are the tumor-suppressor genes in breast cancer." (PMID 35330093, 2022). "Complete coding sequencing of BRCA1/2 in tumor DNA by NGS did not reveal any further BRCA1 somatic PV." (PMID 35039532, 2022). "Somatic tumor testing for BRCA1/2 should be performed in women who do not carry a germline pathogenic or likely pathogenic BRCA1/2 variant." (PMID 36612041, 2022). "There were more basal-like tumours in BRCA1 carriers (50%) than in non-carriers (13%), p = 0.0001, OR = 6.714, 95% CI = [2.058–21.910]." (PMID 35202192, 2022). "The roles of BRCA1 in genetic stability, such as homologous recombination-based double-strand break (HR-DSB) repair and replication fork stabilization, are known to contribute to tumor suppression." (PMID 35327946, 2022). "We first investigated the involvement of alternative non‐homologous end joining (A‐NHEJ) in these repair events because tumours lacking BRCA1/2 have been reported to rely on this pathway for their survival." (PMID 35107878, 2022). "Although we have determined that CNV analysis utilizing ev- and cfDNA is not favorable, we have actually detected the same BRCA1 CNVs in tumor- and evDNA, including the heterozygous deletion, in four out of nine patients and none in cfDNA." (PMID 35205822, 2022). "Tumor cell lines lacking functional BRCA1 and BRCA2 genes had increased sensitivity to platinum and DNA-damaging agents, such as anthracyclines." (PMID 36613648, 2022). "BC is further classified into several subclasses, characterized by immunohistochemical staining {(e.g., ER, PR, HER2 (ERBB2)}, proliferation marker protein Ki-67 (MKI67), genomic markers (e.g., BRCA1, BRCA2, and PIK3CA), and immunomarkers (e.g., tumor-infiltrating lymphocytes and PD-L1)." (PMID 36232989, 2022). "The key proteins in HR, BRCA1, and BRCA2 are two important tumor suppressors." (PMID 35707004, 2022). "This panel covers 161 genes, including BRCA1 and BRCA2 as well as several BRCAness genes involved in the repair mechanism, but also other genes, which are frequently altered in solid tumors and can contribute to tumorigenesis and tumor progression." (PMID 35251494, 2022).
tumor (continued). "In 2005, two groundbreaking studies observed that tumor cells lacking BRCA1 or BRCA2 were particularly sensitive to PARPi through various mechanisms." (PMID 35740616, 2022). "Another study in wild-type BRCA1 ovarian cancer cells demonstrated that the combined treatment of Olaparib and the CDK9 inhibitor CDKI-73 suppressed colony formation and induced apoptosis, and additionally reduced tumor growth in a xenograft mouse model." (PMID 34207158, 2021). "BRCA1 also is bona fide a haploinsufficient tumor suppressor gene, though its heterozygous expression does not promote spontaneous tumors." (PMID 33670664, 2021). "Cyclin D1 overexpression specifically decreased the proliferation of cells lacking BRCA1 or BRCA2, consistent with the mutual exclusivity of BRCA1/2 mutations and CCND1 amplification in tumours." (PMID 34389725, 2021). "However, recent studies have identified new functions of BRCA1 and BRCA2 in the regulation of transcription and RNA processing relevant to their tumor-suppressive activity." (PMID 33593852, 2021). "It is demonstrated that FGFR2 suppresses BRCA1 via the ERK‐YY1 axis and promotes tumor progression." (PMID 34514747, 2021). "The patients with BRCA1–high expression and small tumor size or negative lymph node also showed an improved OS." (PMID 34068585, 2021). "Concordance of BRCA1/BRCA2 PV identified through germline and tumour testing was explored." (PMID 34503154, 2021). "The increased capacity of UWB 1.289 + BRCA1 to form colonies and the ability to migrate after K.D. of PPP3CC supports the hypothesis of its function as a tumor suppressor." (PMID 34573382, 2021). "One week after irradiation, the overall relative tumor volume (RTVs; treated vs. non-treated) for mice bearing Brca1-mutant tumor allografts was 27.9% for mice treated with X-ray irradiation compared with those left untreated." (PMID 33767581, 2021). "Around 11–18% of OC have germline BRCA1/BRCA2 PV and another 6–9% have a somatic BRCA1/BRCA2 PV in the tumour tissue alone which is not inherited." (PMID 34503154, 2021). "A significant difference was noted in the mean age at time of procedure among women with and without a BRCA1 PV identified in their tumor tissue." (PMID 33030818, 2021). "On the other hand, having a low HRD score in a non-BRCA1/2 tumor was not selective enough to completely omit a PARPi in this group, because there was still demonstrable added value compared to placebo treatment." (PMID 33670893, 2021). "Whereas the distribution of lymph node stage, tumor stage, metastasis score, and CRC subtype across BRCA1 expression levels are in line with our findings that low BRCA1 mRNA correlates with worse outcomes, the distribution of sex and race across these groups is more difficult to explain." (PMID 34611475, 2021).
tumor (continued). "Although defects in other key HRR proteins such as PALB2 account for some of these HRD-positive tumours, it is also important to highlight that some HRR genes, in particular BRCA1 and RAD51C, show high levels of promoter hypermethylation leading to gene silencing in breast and ovarian cancer." (PMID 35008208, 2021). "An important feature of PARP inhibition is that it is associated with increases in CD8+ T-cell infiltration and IFN-γ production in the tumor, which occurs in mouse cancer models independent of their Brca1/2 status." (PMID 33888558, 2021). "In BRCA1/2 defective tumors, PARP pathway usually detects DNA damage and promotes its repair, so its inhibition favors the accumulation of DNA damage responsible for the death of tumor cells." (PMID 34200245, 2021). "This indicates that BRCA1 deletions are the main drivers of tumorigenesis, and so BECN1’s role as a tumor supressor remains unclear." (PMID 33459128, 2021). "This was expected, as tumor testing was not completed for prevalent cases with known germline BRCA1/2 PV." (PMID 33030818, 2021). "This was not the case with the syngeneic BRCA1 mut murine model; the difference in elicited response to ICI is the result of a dissimilar effect in both adaptive and innate immune activation, further proven by direct examination between BRCA1 and BRCA2 mut yielded tumor programs." (PMID 34195090, 2021). "While BRCA1 and BRCA2 are known tumor suppressor genes, they may also function as regulators of cell proliferation and/or cell survival during mouse embryogenesis." (PMID 33854442, 2021). "In contrast, 5 patients with BRCA1, BRCA2, and PALB2—all found in patients with tumor types not known to be associated with GPVs in these genes—did not have second hit and are unlikely to respond to PARP inhibitors." (PMID 34792595, 2021). "Estimated coefficient of hazard ratios (HR) correlated to hypermethylated BRCA1 promoter and methylation status conversion (reference: unmethylated) and residual tumor after surgery (reference: none), along with 95% CI and P‐value." (PMID 34601813, 2021). "BRCA1 and BRCA2 are tumour suppressor genes that code for DNA repair proteins." (PMID 34649841, 2021). "We found that PDGFRβ, PKCα, FRA1, and VIM were readily detected in ER− and BRCA1 weak or non-detectable tumor cells, whereas these proteins were barely detectable in ER+ and BRCA1+ tumor cells." (PMID 33478572, 2021). "Second, only somatic variants of BRCA1 and BRCA2 were sequenced, while germline mutations were not assayed as only tumor tissues were tested." (PMID 33632156, 2021). "Of the 398 IHC pairs, multivariate Cox regression analyses showed that CSNK1E↓-SHC1(N)↓, CSNK1E↓-RB1(N)↑, and BRCA1(N)↓-SHC1(N)↓ were significant predictors of the risk of death in this Taiwanese OSCC population, independent of tumor stage." (PMID 33936170, 2021). "In several studies, cases showing BRCA1/2 negative status in the primary tumor and a subsequent BRCA1/2 positive relapse are described." (PMID 34202525, 2021). "Among BRCA1/2 wild-type tumors, both BRIP1-mutated tumors were Sig3 positive while the RAD51C deleted tumor was Sig3 negative." (PMID 34552099, 2021). "The comprehensive GEM ExTra® report filtered out the BRCA1 (V1804D) and instead found FGFR1 amplification and an FGFR1 fusion which may have been driving the tumor and are targetable by several FGFR inhibitors." (PMID 34504655, 2021). "In conclusion, combination of selinexor and olaparib induces robust anti-tumor activity in vitro and in vivo in TNBC cell lines with or without a BRCA1 mutation." (PMID 34504648, 2021). "The inactivation of BRCA1 and/or BRCA2 induces tumor development." (PMID 33915740, 2021). "Due to the limitations conferred by tumor resistance to novel drugs and the considerations enumerated above, we strongly advocate for further work discovering synthetic lethal partners of BRCA1/2 as well as other non-druggable CPGs." (PMID 34070674, 2021).